LEP (leptin)
Diseases named in the same sentence as LEP in open-access papers (continued):
Sharing a sentence is not in itself a finding about the gene and the disease.
Glucose intolerance (165 papers, 2008 to 2026). Glucose intolerance (GI) can be defined as dysglycemia that comprises both prediabetes and diabetes. "It is well known that glucose intolerance associated with high‐fat feeding leads to increased insulin and leptin, as well as decreased HMW‐adiponectin, in serum." (PMID 37845194, 2023). "In our model of early SMAFLD, we observed that the combination of an obesogenic diet and alcohol caused more weight gain, promoted glucose intolerance, and contributed to steatosis by dysregulating leptin/AMPK signaling." (PMID 37134024, 2023). "Hypothalamic ER stress activated IKKβ/NF-κB signaling, causing inflammation, glucose intolerance and central insulin and leptin resistance." (PMID 36188456, 2022). "In leptin-deficient Ob/Ob mice, Adig deficiency only modestly impairs fat mass accrual but does exacerbate glucose intolerance." (PMID 33691105, 2021). "Oral immunization against liver-extracted proteins was associated with a shift from a Th1 to Th2 immune reaction, leading to the amelioration of NASH and glucose intolerance in the leptin-deficient mouse model." (PMID 21042596, 2010). "Additionally, HFD and stress combination induced more profound glucose intolerance associated with increased plasma corticosterone (p < 0.01) and leptin (8.63 ± 0.38) levels." (PMID 38867382, 2024). "Malnutrition-induced epigenetic changes could cause weight and fat mass gain, glucose intolerance, hypertriglyceridemia, abnormal adiponectin, and leptin levels in metabolisms in the offspring." (PMID 35811949, 2022). "In addition, the association of both conditions was responsible for glucose intolerance and oxidative stress in the first generation and increased fetal leptin levels in the second generation." (PMID 35706903, 2022). "However, as the gestation progresses the effect of placenta peptides; Progestrone, estradiol, leptin and glycated haemoglobinon insulin predisposes the women to glucose intolerance and eventually to overt GDM." (PMID 28732072, 2017). "Last, we aimed to evaluate whether GOAT ablation could rescue the massive glucose intolerance of leptin-deficient ob/ob mice." (PMID 23630616, 2013). "A HFD caused abnormal adipocyte hypertrophy, decreased the expression of adiponectin and leptin, and led to glucose intolerance in Ebf2E165X/+ mice." (PMID 41615236, 2026). "Although leptin enhances peripheral insulin sensitivity and β-cell function and suppresses food intake via signaling satiety in the non-pregnant state, pregnancy is associated with progressive leptin insensitivity which may promote insulin insensitivity and glucose intolerance." (PMID 40235646, 2025). "Knockdown of CaSR in adult mice specifically in the hypothalamic arcuate nucleus, where GHRH, POMC and AgRP neurons reside, also resulted in increased body weight, adiposity, leptin resistance, and glucose intolerance, and reduced bone mass." (PMID 40501942, 2025). "We ascribed this leptin insensitivity to the general hypothalamic dysregulation that leads to growth retardation, glucose intolerance, and increased intrabdominal fat mass seen in the NeuronCaSR−/− mice." (PMID 40501942, 2025). "Systemic chemical inhibition of CXCR3 led to significant metabolic changes, including increased body mass, reduced energy expenditure, elevated blood leptin, glucose intolerance, and decreased insulin levels." (PMID 39535032, 2024). "Specifically, 17βE2 protected against HFD-induced increases in body weight, plasma leptin, and glucose intolerance most strongly in APOE4/4 mice." (PMID 39347015, 2024). "Further, Sirt5-knockdown mice showed marked abnormalities in glucose and lipid metabolism, manifested by increased serum triglyceride and leptin levels, glucose intolerance, and decreased insulin sensitivity and adiponectin levels." (PMID 39408844, 2024). "For HFD-induced increases in body weight, plasma leptin, and glucose intolerance, 17βE2 was more beneficial in APOE4/4 mice." (PMID 39347015, 2024).
Glucose intolerance (continued). "It prevents diet-induced obesity (DIO) by increasing leptin signaling through the STAT3 pathway, but it participates in glucose intolerance (GI) by decreasing leptin signaling through the PI3K/AKT pathway." (PMID 38716728, 2024). "High fat diet contributed to increased body weight, serum leptin levels and development of glucose intolerance for both HDM and saline treatment groups." (PMID 36926031, 2023). "This investigation revealed that the SL extract reduced weight gain and WAT weight, reduced LDL-C, leptin, and improved glucose intolerance." (PMID 36839173, 2023). "HFD leads to weight gain, which results in increased mechanical stress on the joints, systemic inflammation, glucose intolerance, and an increase in local leptin signaling." (PMID 38203314, 2023). "ST extract administration decreased weight gain, white adipose tissue weight, LDL-cholesterol, and serum leptin levels while improving glucose intolerance." (PMID 36010531, 2022). "Our animal model reveals that rats suckled for extended periods are protected against HFD-induced weight gain, glucose intolerance and leptin resistance in adulthood compared with rats suckled for the standard period." (PMID 35879461, 2022). "Mice with double deletion of p66Shc and leptin were glucose intolerant like leptin knockout mice, but the double knockout mice showed a lesser degree of glucose intolerance and better insulin sensitivity." (PMID 36465704, 2022). "Although the adipokines leptin and adiponectin improve insulin sensitivity, others contribute to the development of glucose intolerance, including visfatin, fetuin-A, resistin, and plasminogen activator inhibitor-1 (PAI-1)." (PMID 35056647, 2022). "Perinatal exposure of pregnant C57BL6/J mouse dams led to increased leptin levels, glucose intolerance, and increased fat storage in adulthood, confirming DBT’s obesogenic effects in a complex organism." (PMID 34899613, 2021). "That is, HFD-TMP decreased glucose intolerance and leptin level significantly compared to the HFD-SP." (PMID 33807173, 2021). "Glucose intolerance, reduced insulin sensitivity and impaired hypothalamic leptin signaling was identified in male offspring." (PMID 33382823, 2020). "Previously we showed that a brief HFHS diet 1 week before and during pregnancy resulted in glucose intolerance, decreased beta cell numbers and serum insulin levels, and increased leptin and triglyceride levels." (PMID 33257770, 2020). "When examined on days 16–18 of pregnancy, females exposed to BPA revealed glucose intolerance and elevated levels of plasma insulin, triglycerides, and leptin relative to controls." (PMID 30787907, 2019). "Leptin, resistin and visfatin are significantly increased between 11 and 13 weeks of gestation in pregnant women with glucose intolerance and these biomarkers can be used in combination with maternal characteristics for the early prediction of GDM." (PMID 31836012, 2019). "We found that short-term (4–9 days) HFD feeding resulted in modest signs of glucose intolerance and elevated fasting blood glucose concentration, visceral adiposity, and plasma leptin concentration." (PMID 31427627, 2019). "Collectively, pigs born with LBW had a distinct hypothalamic leptin signaling to a high nutrient dense diet, which contributed to greater energy intake and glucose intolerance." (PMID 29615796, 2018). "These mice exhibit a typical 20% increase in body weight, develop glucose intolerance with the concomitant increases in insulin and leptin levels and decreased adiponectin levels." (PMID 29449530, 2018). "We found that exogenous testosterone replacement injected subcutaneously into castrated male db/db mice alleviated the exacerbation of fatty liver and glucose intolerance, suggesting a leptin-independent mechanism." (PMID 29895265, 2018).
Glucose intolerance (continued). "While rapamycin-mediated glucose intolerance was unaffected by metformin in males, we found metformin prevented rapamycin-mediated reduction in insulin and leptin concentrations following 9 months of co-treatment." (PMID 29579736, 2018). "This suggests that the mice were able to overcome their genetically-determined leptin resistance and prevent excess weight gain and glucose intolerance during pregnancy." (PMID 28338021, 2017). "We believe that the mice strains used in this study have possibly adapted to leptin resistance during pregnancy, and therefore avoid glucose intolerance." (PMID 28338021, 2017). "Our previous report demonstrated that BAFF deficiency prevents mice from HF diet-induced glucose intolerance at least in part by potentiating brown adipose tissue function, particularly through enhancement of FGF21 expression and leptin action." (PMID 27814392, 2016). "It is likely that reduced food intake leads to a reduction in fat deposition that in turn reduces pro-inflammatory cytokines, glucose intolerance and improves leptin sensitivity." (PMID 24675731, 2014). "When pregnant mice were treated with BPA on GD9–GD16, they developed glucose intolerance and elevated levels of plasma insulin, triglycerides, glycerol, and leptin compared with control pregnant mice." (PMID 20488778, 2010). "Leptin145E/145E mice cleared glucose less efficiently than Leptin+/+ mice did, indicating glucose intolerance in Leptin145E/145E mice." (PMID 21151569, 2010). "Furthermore, the increase in fat mass in HFD mice was also accompanied by glucose intolerance and higher insulin and leptin plasma concentrations compared to SD mice." (PMID 40001261, 2025). "Moreover, Epac2–/– mice weighed significantly higher and developed more severe intraperitoneal glucose intolerance upon feeding a HFD due to enhanced leptin resistance." (PMID 36329549, 2022). "Induces increased lipid accumulation, fat storage, leptin levels, and glucose intolerance." (PMID 34899613, 2021). "Collectively, these results demonstrate that, compared to normal birth weight pigs, low birth weight pigs had a different hypothalamic leptin and inflammatory response to a high nutrient dense diet, which contributed to greater energy intake and glucose intolerance." (PMID 29615796, 2018). "Therefore, the high concentration of carbohydrates in the high palatability feed possibly contributes to increased body weight, adiposity, adipocyte area, leptin level, glucose intolerance, and hypercholesterolemia." (PMID 28018521, 2016). "Because F0-BPA100 mice presented milder glucose intolerance and higher levels of leptin than F0-BPA10 mice, this may influence birth weight and therefore glucose homeostasis of offspring." (PMID 20488778, 2010). "Therefore, we hypothesized that XYS may regulate depressive-like behavior and glucose intolerance via the leptin and its cascade LepR-STAT3/PI3K pathway in the ARC." (PMID 37046230, 2023). "Therefore, the improvement of blood pressure, leptin, glucose intolerance, etc. may be attributable to appetite suppression related weight loss." (PMID 29618822, 2018). "Also, hepatic knockout of SIRT1 fails to alter serum insulin and leptin levels and shows normal insulin sensitivity and fuel metabolism in white adipose tissue and muscle and thus does not cause systemic glucose intolerance." (PMID 24009212, 2013). "This meta-analysis demonstrated that administration of L-carnitine in diabetic and glucose intolerance patients can significantly reduce TG, LDL-C, FBG, HbA1c, HOMA-IR, CRP, TNF-α, weight, BMI, BFP, and leptin levels." (PMID 39085907, 2024). "PAR4-/- mice developed less visceral adiposity and glucose intolerance under HFD, featuring smaller adipocytes, fewer macrophages and lower expression of adipogenic (leptin, PPARγ) and pro-inflammatory genes (CCL2, IL-1β) in WAT." (PMID 38652276, 2024).
Glucose intolerance (continued). "The results showed that none of the dietary supplements affected weight gain, but HSH partially suppressed glucose intolerance, while HMB and HMH suppressed leptin increase in the adipose tissue." (PMID 37367668, 2023). "Male mice with POMC-specific deletion of inositol-requiring enzyme 1 (IRE1α) showed attenuated leptin and insulin response in POMC neurons and developed glucose intolerance despite normal body weight on chow diet." (PMID 36120438, 2022). "Exposure during pregnancy in women causes glucose intolerance and high levels of insulin, triglycerides, and leptin in plasma compared to the control group, which seems to indicate that exposure to BPA during pregnancy promotes glucose intolerance." (PMID 34200822, 2021). "In addition, our data suggests that desacyl ghrelin may not be a major regulator of glucose or energy homeostasis, at least not in a model of leptin-deficiency with its massive body adiposity and glucose intolerance." (PMID 23630616, 2013). "Glucose intolerance was intensified by the end of the treatment, with no changes in basal glycemia and plasma leptin and insulin levels." (PMID 37616199, 2023). "The TrspRIPKO mice gained more excess weight, while on an HFD, compared to Trsp floxed control mice lacking Cre recombinase, and displayed glucose intolerance, hypothalamic leptin resistance, and systemic insulin resistance." (PMID 36499772, 2022). "We found that the effects of palmitoylated PrRP31 on food intake and BW but not on glucose intolerance require intact leptin signaling." (PMID 34867411, 2021). "HF diet resulted in expected metabolic alterations across groups (increased body and fat mass; glucose intolerance; increased plasma insulin and leptin, decreased ghrelin; nonalcoholic fatty liver disease-related pathology)." (PMID 32993686, 2020). "Thus, despite lower caloric intake, B6 mice challenged with HFD presented increased BW, leptin levels and glucose intolerance compared to the CD group, whereas 129 mice did not present any significant changes when challenged with different diets." (PMID 39536822, 2024). "Although ablation of leptin from all adipocytes may entail global metabolic changes, mutant mice displayed only a subtle weight gain, and no systemic glucose intolerance in the short term of 6 weeks after recombination could be observed." (PMID 37989315, 2023). "We analyzed whether age, BMI, fat distribution (waist-hip ratio), OSA severity (AHI, dessaturation index, minimum 02 saturation), serum lipids and glucose intolerance could be correlated with basal serum leptin levels or not." (PMID 18828917, 2008). "Median of leptin and FGF21, but not of FGF23, were statistically higher in patients with DMT2 and fasting glucose intolerance." (PMID 32570721, 2020).
steatosis (129 papers, 2007 to 2026). Increased lipid within the cytoplasm of cells. "Quantitative ultrasound-based steatosis measures mirrored these associations, with leptin explaining nearly one-fifth of CAP variance among MASLD participants." (PMID 40956476, 2025). "In this study, we explored how the livers of leptin-deficient (ob/ob) mice respond to excessive food intake by initiating harmful cellular processes such as adipogenic steatosis and mitochondrial dysfunction and evaluated the therapeutic effects of melatonin." (PMID 39201365, 2024). "One study including 72 children with biopsy proven MASLD found hyperleptinemia to be associated with an increased risk of developing MASLD and leptin levels increased as steatosis was more severe." (PMID 39201901, 2024). "It has been reported that metformin ameliorates hepato-steatosis and liver dysfunction in ob/ob mice, and in a leptin-deficient mouse model." (PMID 36737598, 2023). "Reduction in leptin levels and steatosis are associated with weight loss mediated by the treatment of drugs that alleviate oxidative stress and reduce lipotoxicity." (PMID 36674935, 2023). "In the liver, CHOP protein suppression has similarly been associated with steatosis occurrence, excessive lipids accumulation within hepatocytes and generally establishment of leptin resistance." (PMID 37020593, 2023). "It has been reported that hypoxia decreases blood levels of glucose, cholesterol, and basal Leptin, results in fat loss, and prevents steatosis in obese mice." (PMID 35563600, 2022). "Increasing recent evidence indicates that leptin signaling is also implicated in the development of various liver diseases, including steatosis, hepatitis, and fibrosis." (PMID 34830465, 2021). "Leptin-deficient mice are predisposed to develop severe steatohepatitis with macrovesicular steatosis; however, when maintained on a standard chow diet, they do not develop fibrosis." (PMID 33324348, 2020). "On the other hand, some authors observed increased mitochondrial beta-oxidation in the liver of leptin deficient mice (ob/ob) with severe steatosis." (PMID 26788524, 2016). "Our results showed that livers from leptin-deficient mice expressed significantly higher levels of both PPARγ (15-fold) and PPARα mRNA (>1.5-fold), suggesting that ob/ob mice exhibited increased hepatic adipogenesis and steatosis." (PMID 39201365, 2024). "IR and steatosis contribute to the proinflammatory and profibrogenic actions of leptin, which may be attributed to human variants of the Lep-R gene." (PMID 38738048, 2024). "Leptin may be implicated in steatosis progression via activation of the PI3-K/Akt kinase pathway via OB-R." (PMID 34988225, 2021). "Another critical mechanism by which leptin is implicated in altered lipid metabolism and contributes to the initial development of steatosis and to NASH progression is directly related to hepatic iron metabolism, which promotes lipid peroxidation and alters insulin signaling." (PMID 33316927, 2020). "In addition, chronic liver ER stress was observed in the steatosis of mice strains with genetically deficient in leptin as well as genetically modified IRE1/XBP1, PERK/eIF2α and ATF6 signaling pathways." (PMID 32121602, 2020). "Next, leptin-deficient genetically obese (ob/ob) mice were used as a model for steatosis." (PMID 23849208, 2013). "Therefore, as a consequence, the massive production of pro-inflammatory cytokines in hepatic cells (i.e., hepatocytes and Kupffer cells) leads to the alteration of the leptin/adiponectin ratio and promotes the conversion of steatosis into steatohepatitis causing liver damage progression." (PMID 33265944, 2020). "However, leptin signalling is disrupted in hepatic steatosis, causing leptin resistance." (PMID 31842467, 2019). "Previously, we have shown that a similar diet regimen resulted in changes in the periphery in AD males and females: hepatic fibrosis, steatosis, and increases in circulating leptin." (PMID 41282259, 2025).